GPR148 (G protein-coupled receptor 148)
Description:
Orphan receptor.
Synonyms: BTR; PGR6
Tractability: Small molecule: it belongs to a druggable protein family. Antibody: its Gene Ontology location is reachable by antibodies, with high confidence; UniProt places it where antibodies can reach, with medium confidence; UniProt predicts a signal peptide or a membrane-spanning region; the Human Protein Atlas places it where antibodies can reach.
Target class: Family A G protein-coupled receptor; Membrane receptor
Gene: Protein-coding gene on chromosome 2 (130,729,070 to 130,730,336, forward strand). Ensembl gene ENSG00000173302.
Subcellular location: Cell membrane
Subcellular location (Human Protein Atlas): Plasma membrane
Gene Ontology:
Molecular function: protein binding; odorant binding; olfactory receptor activity; G protein-coupled receptor activity
Biological process: detection of chemical stimulus involved in sensory perception of smell; G protein-coupled receptor signaling pathway
Cellular component: plasma membrane; membrane
Genetic constraint (gnomAD): Loss-of-function variants: 0 observed, 0.35 expected, observed/expected ratio (o/e) 0, 90% interval 0 to 1.86. That is too few expected variants to judge how well the gene tolerates losing a copy. Missense variants: 424 observed, 437.54 expected, observed/expected ratio (o/e) 0.97, 90% interval 0.89 to 1.05. Synonymous variants: 173 observed, 187.61 expected, observed/expected ratio (o/e) 0.92, 90% interval 0.81 to 1.05.
Homologues: Orthologues: chimpanzee GPR148 (99% identical). Paralogues in human: EDNRB (21% identical), NMUR1 (19% identical), MLNR (18% identical), NTSR1 (18% identical), EDNRA (18% identical), GHSR (17% identical), NTSR2 (17% identical), NMUR2 (16% identical), TRHR (16% identical), NMBR (14% identical), BRS3 (13% identical), GPR39 (13% identical), and 3 more.